PTCRA (pre T cell antigen receptor alpha)
Description:
Component of the pre-T-cell receptor complex (composed of PTCRA, TCRB and the CD3 complex) that has a crucial role in early T-cell development, particularly alpha-beta T cell differentiation.
Synonyms: pT-alpha; pTa; IMD126
Tractability: Antibody: UniProt places it where antibodies can reach, with high confidence; its Gene Ontology location is reachable by antibodies, with high confidence; UniProt predicts a signal peptide or a membrane-spanning region.
Gene: Protein-coding gene on chromosome 6 (42,915,989 to 42,925,838, forward strand). Ensembl gene ENSG00000171611.
Subcellular location: Membrane; Cell membrane
Pathways (Reactome):
Signal Transduction: NOTCH3 Intracellular Domain Regulates Transcription
Gene Ontology:
Molecular function: protein binding
Biological process: alpha-beta T cell differentiation; negative regulation of thymocyte apoptotic process
Cellular component: plasma membrane; membrane
Genetic constraint (gnomAD): Loss-of-function variants: 10 observed, 14.52 expected, observed/expected ratio (o/e) 0.69, 90% interval 0.42 to 1.17. The upper end of that interval is the gene's LOEUF score, 1.17, which puts it in group 5 of 6, group 1 being the genes least tolerant of losing a copy. Missense variants: 353 observed, 340.61 expected, observed/expected ratio (o/e) 1.04, 90% interval 0.95 to 1.13. Synonymous variants: 153 observed, 150.97 expected, observed/expected ratio (o/e) 1.01, 90% interval 0.89 to 1.16.
Gene-disease validity (ClinGen):
ClinGen rates the evidence that PTCRA causes each of these diseases.
immunodeficiency 126, susceptibility to (autosomal recessive): Strong.
Homologues: Orthologues: chimpanzee PTCRA (96% identical), macaque PTCRA (90% identical), pig PTCRA (49% identical), mouse Ptcra (47% identical), rat Ptcra (42% identical), dog PTCRA (37% identical).
Diseases named in the same sentence as PTCRA in open-access papers:
PTCRA is named in the same sentence as 10 diseases in open-access papers, as found by Europe PMC text mining. Sharing a sentence is not in itself a finding about the gene and the disease. The quoted sentences say what the papers report.
Autoimmunity (2 papers, 2016 to 2024). The occurrence of an immune reaction against the organism's own cells or tissues. "Homozygosity for hypomorphic mutations of PTCRA should be considered in patients with isolated autoimmunity, particularly the p.Asp51Ala substitution in individuals of South Asian or Middle Eastern origin." (PMID 38422122, 2024).
breast carcinoma (2 papers, 2021). "The Pre T Cell Antigen Receptor Alpha (PTCRA) has recently been nominated as a biomarker in breast cancer." (PMID 33573289, 2021).
acute promyelocytic leukemia (1 paper, 2016). An aggressive form of acute myeloid leukemia (AML), characterized by arrest of leukocyte differentiation at the promyelocyte stage, due to a specific chromosomal translocation t(15;17) in myeloid cells. "It was shown that PTCRA is expressed in acute promyelocytic leukemia significantly." (PMID 26822197, 2016).
chronic myelogenous leukemia (1 paper, 2021). "Research has shown that variation of PTCRA may be related to the prognosis of patients with chronic myelogenous leukemia." (PMID 34395274, 2021).
cancer (5 papers, 2012 to 2022). A tumor composed of atypical neoplastic, often pleomorphic cells that invade other tissues. "These variants were found in genes associated with cancers (ANKRD35, DNAH9, MAGEC1, TOX3) or participating in cancer-related signaling pathways (THSD1, MORN2, PTCRA)." (PMID 26822197, 2016).
tumor (2 papers, 2022). "The genes with low expression in the tumor group were CRISP3, FAM3D, SCNN1B, CRISP2, RBM20, PHYHIP, C2orf54, SLC5A1, PTCRA, C15orf59, and ANO10." (PMID 35389773, 2022).
infection (1 paper, 2007). The state of being infected such as from the introduction of a foreign agent such as serum, vaccine, antigenic substance or organism. "While these comparisons were complicated by the general paucity of detailed annotations of the early response genes, the limited annotations suggest PTCRA is linked to TCF3 in cluster 3, which is up-regulated 1.5 hours post infection." (PMID 18047719, 2007).
PTCRA also shares sentences with these, for which no sentence is quoted: leukemia (1 paper); osteoporosis (1); viral infections (1).